GNL3 (G protein nucleolar 3)
Diseases named in the same sentence as GNL3 in open-access papers:
GNL3 is named in the same sentence as 25 diseases in open-access papers, as found by Europe PMC text mining. Sharing a sentence is not in itself a finding about the gene and the disease. The quoted sentences say what the papers report.
schizophrenia (8 papers, 2018 to 2025). A major psychotic disorder characterized by abnormalities in the perception or expression of reality. "Many risk genes shared by schizophrenia and BD have been reported to affect dendritic spine morphogenesis, such as NEK4, GNL3, PBRM1, and GLT8D1." (PMID 37443018, 2023). "This region harbours genes including ITIH4, NEK4, GNL3 and PBRM1 that have previously been linked mechanistically to schizophrenia and related brain changes at cellular and whole brain scales." (PMID 38016951, 2023). "The genomic region of chromosome 3p21.1 contained several genes pleiotropically associated with both SA and schizophrenia, including PBRM1, NEK4, GNL3, ITIH4 and NISCH." (PMID 38016951, 2023). "Recently, a study found that the genetic variants in the 3p21.1 region affect expression of NEK4, GNL3, and PBRM1 in the frontal cortices, which in turn affected dendritic spines, cognitive function, schizophrenia, and bipolar disorder." (PMID 34291596, 2021). "In fact, CEWAS also detected GNL3, SPCS1, and TMEM110 for intelligence with z-scores having opposite signs compared to schizophrenia, which aligns with how risk alleles in these loci were previously shown to correlate with lower cognitive test scores." (PMID 34807913, 2021). "Similar to GNL3, SPCS1 and TMEM110 also lie in the 3p21.1 region, and their expression levels were previously shown to be associated with risk variants of schizophrenia, bipolar disorder, and depression." (PMID 34807913, 2021). "Fittingly, overexpression of GNL3 was previously shown to reduce the density of mushroom dendritic spines in rats, which might relate to dendritic spine pathology observed across patients with schizophrenia, bipolar disorder, and depression." (PMID 34807913, 2021). "In addition, a transcript annotated to GNL3, encoding G Protein Nucleolar 3, was associated with both bipolar disorder (P-SMR = 2.17 × 10− 6) and schizophrenia (P-SMR = 2.71 × 10− 7), with risk alleles for both disorders associated with increased expression of this transcript in fetal brain." (PMID 30419947, 2018). "Brain expression analysis found significant effects on GNL3 and ITIH4 expression in prefrontal cortices, explaining the observed aberrant brain activity in schizophrenia." (PMID 34291596, 2021).
bipolar disorder (6 papers, 2010 to 2025). A disorder of the brain that causes unusual shifts in mood, energy, activity levels and the ability to carry out day-to-day tasks. "GNL3 and genes in the vicinity of 3p21.1 are known to influence alpha oscillations and are associated with clinical risk for SZ and bipolar disorder, suggesting a mechanistic link between GNL3, abnormal alpha rhythms, and risk for SZ." (PMID 40806641, 2025). "GNL3/Nucleostemin, is a gene implicated in cell cycle/growth/progression, neural progenitor activity, which has also been linked to bipolar disorder." (PMID 21152067, 2010). "GNL3 (3p21.1) sits in a genomic region strongly linked through GWAS to SZ and bipolar disorder." (PMID 40806641, 2025).
prostate carcinoma (4 papers, 2021 to 2026). A carcinoma that arises from epithelial cells of the prostate gland. "A number of studies have also described the association of GNL3 gene overexpression with tumor progression and poor survival in cancer of the prostate, stomach, colon, breast, and lung." (PMID 34205581, 2021). "A progressive increase in the expression of GNL3 and PA2G4 was observed during cancer progression having significant association with poor survival in prostate cancer patients." (PMID 37345060, 2023). "In prostate cancer, aberrant expression of GNL3 and PA2G4 correlate with tumorigenesis and metastasis." (PMID 37345060, 2023). "We found that the higher expression of GNL3, CHCHD8, PA2G4, and RRP9 genes with HR more than 1.0 was closely associated with poor overall survival and disease-free survival in prostate cancer patients." (PMID 37345060, 2023). "GNL3 is highly expressed in central nervous system (CNS) stem cells, embryonic stem cells, and some tumor cell lines (such as prostate cancer cell lines)." (PMID 35432540, 2022). "Using a bioinformatics approach, we predicted GNL3 and PA2G4 as biomarkers of prognostic significance in prostate cancer." (PMID 37345060, 2023). "Based on the published information and our bioinformatics approach, we propose GNL3 and PA2G4 as prognostic biomarkers in prostate cancer." (PMID 37345060, 2023). "In our differential expression analysis, we found that CHCHD8, GNL3, PA2G4, and RRP9 have 27.0-, 38.6-, 12.8-, and 7.6-times higher expression in prostate cancer specimens in comparison to normal prostate tissue." (PMID 37345060, 2023). "GNL3 and PA2G4 have been found to be overexpressed in several human cancers, including prostate cancer." (PMID 37345060, 2023). "We found that GNL3 and PA2G4 showed comparatively significant and better performance in prostate cancer specimens compared to normal samples." (PMID 37345060, 2023). "This review article mainly highlights the function of GNL3 and PA2G4 and focuses on the opportunities for their development as prognostic biomarkers in prostate cancer." (PMID 37345060, 2023). "The GNL3, CHCHD8, PA2G4, and RRP9 genes were selected to predict their ability in overall and disease-free survival in prostate cancer patients." (PMID 37345060, 2023). "Based on the information CHCHD8, GNL3, PA2G4, and RRP9 genes were selected to further explore the prognostic significance in prostate cancer." (PMID 37345060, 2023). "Overall, our analysis predicted GNL3 and PA2G4 as prognostic biomarkers of clinical significance in prostate cancer." (PMID 37345060, 2023). "Clinical data suggest that GNL3 and PA2G4 could be developed as prognostic biomarkers of clinical significance in prostate cancer." (PMID 37345060, 2023). "Based on our analysis, GNL3 and PA2G4 showed better performance as prognostic biomarkers and may be used separately or in combination in prostate cancer." (PMID 37345060, 2023).
colon carcinoma (3 papers, 2020 to 2021). "GNL3 has upregulated expression in colon cancer and plays an important role in tumor growth, invasion, and metastasis." (PMID 34712323, 2021). "GNL3 promotes the transformation of colon cancer epithelial cells to mesenchymal cells by activating the Wnt/β-catenin signaling pathway." (PMID 34712323, 2021). "GNL3 can promote colon carcinoma cell proliferation, invasion and migration by activating the Wnt/β-catenin signaling pathway." (PMID 32087603, 2020). "GNL3 is upregulated in colon carcinoma cell and tissue, and facilitate tumor cell epithelial-mesenchymal transition by activating the Wnt/β-catenin signaling pathway." (PMID 32071816, 2020).
hepatoma (2 papers, 2006 to 2022). "The effect of GNL3 on the proliferation of hepatocellular carcinoma was detected in a subcutaneous tumor-bearing animal model." (PMID 35432540, 2022). "In conclusion, this study found that GNL3 increased expression in hepatocellular carcinoma, which promoted the malignant biological behavior of hepatocellular carcinoma cells and was related to the cell dry phenotype." (PMID 35432540, 2022). "Transwell chamber assays were used to detect the effects of GNL3 on the migration and invasion of hepatocellular carcinoma cells." (PMID 35432540, 2022). "This study also investigated the role of GNL3 in the malignant biological behavior of hepatocellular carcinoma cells." (PMID 35432540, 2022). "The expression of GNL3 in hepatocellular carcinoma was detected, and its effect on the proliferation and metastasis of hepatocellular carcinoma cells was investigated." (PMID 35432540, 2022). "CCK-8 assays showed that the growth rate of hepatoma cells in the GNL3 overexpression group was significantly higher than that in the NC group." (PMID 35432540, 2022). "This study further analysed the stem cell-like properties and mechanism of GNL3 through SIRT1 in hepatocellular carcinoma cells." (PMID 35432540, 2022). "In vivo and in vitro experiments confirmed that silencing GNL3 could inhibit the proliferation, migration, and invasion of hepatocellular carcinoma cells." (PMID 35432540, 2022). "A GNL3 interfering plasmid was constructed, and the effects of GNL3 on the proliferation of HepG2 and PLC-PRF-5 hepatoma cells were detected by the CCK-8 method." (PMID 35432540, 2022). "By silencing GNL3 expression in hepatocellular carcinoma cell lines, CCK-8 and Transwell assays were used to detect GNL3 proliferation and motor invasion ability." (PMID 35432540, 2022).
liver diseases (2 papers, 2020 to 2024). "Moreover, expression of a number genes—potential therapeutic targets in liver diseases—including EGFR, GLUD1, GNL3, and RGS5, has been shown to be modified by dietary fats and should be further investigated in this regard." (PMID 32961898, 2020).
breast carcinoma (1 paper, 2018). "rs1108842 in gene GNL3, rs3785181 in gene GAS11, rs879882 in gene POU5F1 and rs2523608 in gene HLA-B are reported to have a high probable association with tumor or breast cancer." (PMID 30072632, 2018).
COVID-19 (1 paper, 2021). A disease caused by infection with severe acute respiratory syndrome coronavirus 2. "Furthermore, the transcriptome-wide analysis identified six novel loci, among others, consisting of genes—IFIT3, KEAP1, and GNL3 demonstrating their putative association with COVID-19 hospitalization outcome." (PMID 34315903, 2021). "Furthermore, we found evidence for GNL3 eQTL colocalizing with pulmonary function traits such as FEV and FVC which are decreased in COVID-19 patients." (PMID 34315903, 2021).
diabetes (1 paper, 2017). "The obesity SNP rs2710323, together with two diabetes SNPs, rs2590838 (r2, 0.78) and rs1108842 (r2, 0.8), are located in loci that regulate genes (TMEM110, MUSTN1, ITIH4, NEK4, GNL3, PBRM1, and NT5DC2) within a 300 kb genomic region on chromosome 3." (PMID 29081791, 2017).
knee osteoarthritis (1 paper, 2018). "Previous studies have indicated that the GNL3 gene is associated with knee osteoarthritis (KOA) susceptibility in Europeans; however, the exact molecular mechanism is still unclear." (PMID 29942097, 2018).
leukemia (1 paper, 2021). A malignant (clonal) hematologic disorder, involving hematopoietic stem cells and characterized by the presence of primitive or atypical myeloid or lymphoid cells in the bone marrow and the blood. "Accordingly, downregulation of GNL3 expression was able to significantly induce apoptosis in leukemia cellular models." (PMID 33806232, 2021).
liver cancer (1 paper, 2022). An epithelial or non-epithelial malignant neoplasm that arises from the liver. "The relationship between GNL3 and the prognosis of liver cancer was analysed using public databases." (PMID 35432540, 2022). "The results showed that the expression level of the GNL3 gene in liver cancer tissues was higher than that in adjacent tissues." (PMID 35432540, 2022). "Real-time fluorescence quantitative PCR detection results showed that the average expression level of the GNL3 gene in liver cancer tissues was higher than that in adjacent tissues of 20 patient specimens)." (PMID 35432540, 2022). "GEPIA database analysis showed that the high expression of GNL3 was closely related to the poor prognosis of liver cancer, which has important reference value for predicting the prognosis of liver cancer." (PMID 35432540, 2022). "However, the mechanism by which GNL3 regulates the biological behavior of malignant liver cancer remains unclear." (PMID 35432540, 2022). "Why GNL3 is highly expressed in liver cancer and the mechanism has not been explained." (PMID 35432540, 2022).
ovarian tumors (1 paper, 2021). "Moreover, our integrated analysis of gene expression data in ovarian tumors from publicly available databases led us to identify that GNL3 mRNA is aberrantly upregulated in a wide number of OC patients." (PMID 33806232, 2021).
rhabdomyosarcoma (1 paper, 2021). A rare aggressive malignant mesenchymal neoplasm arising from skeletal muscle. "In rhabdomyosarcoma (RMS) cell lines, we recently demonstrated that OTX015 specifically downregulates BRD4 and MYC levels, which in turn lead to a marked downmodulation of GNL3 gene." (PMID 33806232, 2021).
tumor (17 papers, 2018 to 2026). "GNL3 is overexpressed in CRC tumor cells compared to normal colon tissue and is significantly associated with poor patient overall survival." (PMID 33120992, 2020). "Moreover, XBP1 promoted tumor growth and metastasis by binding to the GNL3 (G protein nucleolar 3—a nucleolar protein involved in cell proliferation, cell cycle, and invasion) promoter and fostering its expression." (PMID 41228282, 2025). "These functions might vary depending on the organism, on the stem or tumour cell type, on the microenvironment surrounding GNL3/NS-expressing cells, and on particular cellular burdens such as genotoxic exposure or nucleolar stress." (PMID 36069077, 2022). "Since inefficient apoptosis represents one of the primary mechanisms that lead to drug resistance, GNL3 reduction may likely be a molecular target for OC treatment by reducing tumor growth and dissemination." (PMID 33806232, 2021). "A link could be made between GNL3/NS involvement in organismal growth (; this study) and tumour growth, highlighting the potential that GNL3/NS downregulation could have in developing cancer therapies to reduce tumour growth." (PMID 36069077, 2022). "Functionally, GNL3 knockdown sensitizes CRPC cells to AR antagonists and impairs tumor growth and metastasis." (PMID 41772945, 2026). "In summary, GNL3 and PA2G4 play crucial biological roles in cancer, supporting important cellular processes such as cell migration, proliferation, apoptosis, and tumor growth." (PMID 37345060, 2023). "Concurrently, GNL3 functions as a corepressor of immune-responsive genes such as CXCL10 and TAP1 via class I histone deacetylases (HDACs), thereby facilitating CD8+ T cell elimination and establishing an immunosuppressive tumor microenvironment." (PMID 41772945, 2026). "In addition to chaperones, which were shown to play a significant role for the induction of anti-tumor immune responses, we identified a number of TAAs interacting with NS1 (i.e., TPT1, NUMA1, SPRYD4, SND1, and GNL3)." (PMID 36680249, 2023). "The overexpression of GNL3 in HT29 CRC cells activates the WNT signaling pathway, cell proliferation, colony formation, epithelial-mesenchymal transition (EMT), migration, invasion, and in vivo tumor growth, whereas its suppression by siRNA reverses these effects." (PMID 33120992, 2020).
cancer (10 papers, 2009 to 2023). A tumor composed of atypical neoplastic, often pleomorphic cells that invade other tissues. "Both of the selected genes, Gnl3 from the ribosome biogenesis in eukaryotes and Dctd from the pyrimidine metabolism pathways, are markers predominantly associated with proliferating stem and progenitor cells as well as immortalized cancer cell lines." (PMID 36591261, 2022). "A dysregulated expression of GNL3 has been observed in several cancer cells and it was found to be associated with forced cell growth and survival, increased propensity to metastasize as well as with enhanced resistance to therapies, relapse and poor prognosis." (PMID 33806232, 2021). "Our study helps to highlight the importance of GNL3 in cancer and stem cell research, as well as the significance of studying diverse animals, and of performing wide phylogenetic comparisons, to better understand gene evolution." (PMID 36069077, 2022). "Earlier studies have reported that the elevated expression of GNL3 is related to cancer proliferation and metastasis." (PMID 33014785, 2020). "OTX015 impaired migration capacity and potentiated IR effects by reducing the expression of different drivers of cancer resistance mechanisms, including GNL3 gene, whose expression was found to be significantly higher in OC biopsies than in normal ovarian tissues." (PMID 33806232, 2021). "In the present study, we focused on the molecular mechanisms involved in the antitumor effects exerted by OTX015 in OC cells by demonstrating that BET inhibition reduces cancer cell proliferation and viability through the marked downregulation of GNL3 expression." (PMID 33806232, 2021). "Interestingly, we also applied a computational approach, based on Barabasi-Albert (BA) modelling, to define the GNL3-related network architecture in which connected components are represented by key molecules in cancer biology." (PMID 33806232, 2021). "GNL3 is also a biomarker for many stem cells and cancer cells." (PMID 32635896, 2020). "G protein nucleolar 3 (GNL3) is a nucleolar GTP binding protein that is highly expressed in progenitor cells, stem cells and various types of cancer cells." (PMID 35836256, 2022).
GNL3 also shares sentences with these, for which no sentence is quoted: depression (1 paper); hand osteoarthritis (1); lung adenocarcinoma (1); lung carcinoma (1); neuroblastoma (1); Obesity (1); osteoarthritis (1); ovarian carcinoma (1); viral infection (1).